OR4S2 (olfactory receptor family 4 subfamily S member 2)
Description:
Odorant receptor.
Synonyms: OR4S2P; OST725; OR11-137
Tractability: Antibody: UniProt places it where antibodies can reach, with medium confidence; UniProt predicts a signal peptide or a membrane-spanning region; its Gene Ontology location is reachable by antibodies, with medium confidence.
Gene: Protein-coding gene on chromosome 11 (55,648,327 to 55,652,854, forward strand). Ensembl gene ENSG00000174982.
Subcellular location: Cell membrane
Pathways (Reactome):
Sensory Perception: Expression and translocation of olfactory receptors
Gene Ontology:
Molecular function: olfactory receptor activity; G protein-coupled receptor activity
Biological process: detection of chemical stimulus involved in sensory perception of smell; G protein-coupled receptor signaling pathway
Cellular component: plasma membrane; membrane
Genetic constraint (gnomAD): Loss-of-function variants: 3 observed, 4.02 expected, observed/expected ratio (o/e) 0.75, 90% interval 0.33 to 1.71. That is too few expected variants to judge how well the gene tolerates losing a copy. Missense variants: 140 observed, 143.95 expected, observed/expected ratio (o/e) 0.97, 90% interval 0.85 to 1.12. Synonymous variants: 54 observed, 53.23 expected, observed/expected ratio (o/e) 1.01, 90% interval 0.81 to 1.27.
Homologues: Orthologues: chimpanzee OR4S2 (99% identical), macaque OR4S2 (96% identical), rabbit OR4S2 (91% identical), mouse Or4s2 (90% identical), rat Or4s2 (89% identical), dog OR4S2 (89% identical), mouse Or4s2b (88% identical), guinea pig OR4S2 (87% identical). Paralogues in human: OR4B1 (60% identical), OR4P4 (60% identical), OR4X2 (59% identical), OR4S1 (58% identical), OR4C15 (57% identical), OR4C12 (57% identical), OR4C6 (56% identical), OR4A15 (56% identical), OR4C11 (56% identical), OR4A47 (55% identical), OR4E2 (55% identical), OR4C3 (55% identical), and 116 more.
Diseases named in the same sentence as OR4S2 in open-access papers:
OR4S2 is named in the same sentence as 3 diseases in open-access papers, as found by Europe PMC text mining. Sharing a sentence is not in itself a finding about the gene and the disease. The quoted sentences say what the papers report.
Obesity (5 papers, 2015 to 2025). Accumulation of substantial excess body fat. "Interestingly, a common copy number variant region was identified on chromosome 11q11 associated with obesity and exclusively covering three OR genes, OR4p4, OR4S2 and OR4C6." (PMID 25943692, 2015). "The regions showing association with obesity‐related phenotypes are located at 11q11 (OR4P4, OR4S2, OR4C6), 1p21.1 (AMΥ1), 10q11.22 (NPY4R), 10q26.3 (CYP2E1), 16q12.2 (FTO), 16p12.3 (GPRC5b), and 4q25 and have been associated with adult obesity as well." (PMID 41082226, 2025). "In a genome-wide association study (GWAS), variants of three olfactory genes, OR4P4, OR4S2 and OR4C6, were found to be associated with obesity." (PMID 38248819, 2023). "The block contains a copy number deletion involving OR4P4, OR4S2, and OR4C6 genes which is associated with early extreme obesity in previous studies using genotyping arrays and suggesting the link between olfactory dysfunction and obesity." (PMID 38110883, 2023).
breast carcinoma (2 papers, 2017 to 2021). "Moreover, other common CNVs were found to be associated with breast cancer risk through whole genome CNV genotyping studies including those disrupting OR4C11, OR4P4, OR4S2 and UGT2B17 genes." (PMID 33503040, 2021). "Indeed, this patient harbored several CNVs reported as associated with breast cancer risk involving UGT2B17, OR4C11, OR4P4, OR4S2 and GSTT1 genes." (PMID 33503040, 2021).
OR4S2 also shares sentences with these, for which no sentence is quoted: cancer (1 paper).